CFTR (CF transmembrane conductance regulator)
Diseases named in the same sentence as CFTR in open-access papers (continued):
Sharing a sentence is not in itself a finding about the gene and the disease.
cholera (continued). "In summary, α,β-dehydrolovastatin (DHLV) and other statins represent a novel class of inhibitors of intestinal apical Cl ̄ channels including CFTR and CaCC, which are involved in the pathogenesis of severe diarrheas including cholera." (PMID 36490300, 2022). "Motivated by its antisecretory action in T84 cells, we tested cinacalcet in mouse models of cholera and traveler’s diarrhea in which CFTR activation is the major secretory pathway following exposure to cholera toxin or STa toxin, respectively." (PMID 33400691, 2021). "In conclusion, we demonstrated that the FDA-approved drug cinacalcet suppressed CFTR-mediated Cl– secretion in human colonic T84 cells and prevented diarrhea in mouse models of cholera and traveler’s diarrhea." (PMID 33400691, 2021). "This is true, in particular, for cholera, whose secretory diarrhea depends on the CFTR chloride and SK potassium channels, both of which are calmodulin-dependent." (PMID 28586382, 2017). "One of the major chloride channels, cystic fibrosis transmembrane conductance regulator (CFTR), has been shown to be responsible for the enterotoxin-induced secretory diarrhea in cholera and Travelers’ diarrhea." (PMID 27601995, 2016). "With an attempt to develop anti-secretory therapy of cholera, several classes of CFTR inhibitors have been identified and demonstrated to effectively reduce CT-induced intestinal fluid secretion in both rats and mice." (PMID 25188334, 2014). "To date, several classes of potential antidiarrheal therapeutics for cholera have been identified, with CFTR inhibitor being recognized as the most promising candidate." (PMID 25188334, 2014). "Until now, several classes of CFTR inhibitors have been identified and shown to exhibit antidiarrheal efficacy in animal models of cholera." (PMID 25188334, 2014). "After internalization into enterocytes, cholera toxins induce an elevation of intracellular cAMP and subsequent CFTR-dependent Cl− secretion, resulting in intestinal fluid secretion and fluid loss." (PMID 25188334, 2014). "This study identifies natural statin derivatives as novel natural product-derived CFTR inhibitors, which may be beneficial in the treatment of enterotoxin-induced secretory diarrheas including cholera." (PMID 36490300, 2022). "Thus, as a target for intervention, transient blocking of the CFTR channel function with pharmacological agents remains a promising option not only for cholera but for other diarrheal disease syndromes." (PMID 35324722, 2022). "In antidiarrhea studies, watery stools induced by CT could be significantly inhibited by the oral gavage of plumbagin, proving that plumbagin might be useful in the treatment of diarrhea due to CFTR overactivation, including in cholera and Traveler’s diarrhea." (PMID 31649543, 2019). "Because of the massive intestinal fluid secretion mediated by activation of the CFTR in cholera and enterocyte CaCC in rotavirus infections, we postulated that CFTR and enterocyte CaCC activators would increase intestinal fluid secretion and treat constipation." (PMID 28713271, 2017). "Interestingly, a recent study using a V. cholerae infection model in adult mice confirmed CFTR as a major host factor determining intestinal fluid secretion in cholera." (PMID 25188334, 2014). "Accordingly, CFTR is regarded as a promising drug target for cholera." (PMID 25188334, 2014). "However, the exact therapeutic value of CFTR inhibitor in the treatment of cholera has been elusive, since anti-diarrheal efficacy of CFTR inhibitors has never been investigated in animal models of V. cholerae-induced diarrhea." (PMID 23826402, 2013). "Our results suggest that BPO-27 should advance to human Phase I studies that could further address its safety and efficacy as therapeutic or preventative drug intervention for diarrheal syndromes, including cholera, that are mediated by CFTR channel activation." (PMID 35324722, 2022).
cholera (continued). "Therefore, it may be more reasonable to develop antidiarrheal therapy of cholera by extending clinical applications of known drugs that are found to inhibit CFTR-mediated Cl− secretion." (PMID 25188334, 2014). "These comparative results suggest a lower CFTR-inhibitory capacity of IOWH-032 compared to PPQ-102, supporting the limited efficacy of this inhibitor when used in vivo for the treatment of cholera." (PMID 36899912, 2023). "Here we showed that CaSR regulates CFTR-mediated Cl– secretion in human T84 cells, and the FDA-approved CaSR activator cinacalcet prevents intestinal fluid accumulation in mouse models of cholera and traveler’s diarrhea." (PMID 33400691, 2021). "The antidiarrheal effects of three classes of chemical-molecular CFTR inhibitors, namely, CFTRinh-172, BPO-27, and GlyH-101, have been proven in mouse models of cholera and STa toxin-induced intestinal fluid secretion." (PMID 31649543, 2019). "However, the development of these CFTR inhibitors into new antidiarrheal therapy has progressed slowly, probably, due to the limited financial incentives for the investment in research and development of drugs for cholera, which is prevalent in developing countries." (PMID 25188334, 2014). "Both in vitro and in vivo experiments demonstrated that cystic fibrosis transmembrane conductance regulator (CFTR) mediates CT-induced apical Cl− efflux into intestinal lumen and therefore represents a promising therapeutic target for treatment of cholera." (PMID 23826402, 2013). "Aside from CT, V. cholerae secretes many other toxins and virulence factors that do not target CFTR but contribute substantially to the pathogenesis of cholera." (PMID 33113586, 2020). "Crofelemer is thus unlikely to be beneficial in secretory diarrheas such as cholera and Traveler's diarrhea in which CFTR is the major Cl− secretory pathway and in which fluid secretion is very high." (PMID 24551253, 2014). "Pathogenesis of diarrhea in this cholera model results from CFTR-mediated transepithelial Cl− secretion with no involvement of disrupted intestinal barrier function or vascular leakage." (PMID 23826402, 2013). "Additionally, using a mouse model, an investigation conducted by Gabriel and colleagues showed that heterozygotes for non-functioning CFTR alleles were resistant to cholera toxin which suggests that increased resistance to cholera may also explain the persistence of CF." (PMID 22151998, 2011).
respiratory infections (34 papers, 2010 to 2026). "One of the most complex and evolving aspects of corticosteroid therapy in CF relates to how CFTR modulators influence the risk and nature of respiratory infections." (PMID 41154689, 2025). "Carriers of CFTR mutations also experience increased rates of respiratory infections and hospitalisations, with potential risks of antibiotic resistance due to frequent infections." (PMID 40241998, 2025). "For example, common heterozygous CFTR mutations are associated with increased risk of respiratory infections." (PMID 36377664, 2022). "Despite individuals that are heterozygous for CFTR mutations exhibit only a partial reduction in CFTR function, they remain more susceptible to respiratory infections than the general population." (PMID 32192506, 2020). "Disease causing CFTR gene mutations are responsible for the respiratory symptoms associated with CF, namely the production of thick, sticky mucus in the airways which is difficult to clear and leads to recurrent respiratory infections." (PMID 41220810, 2024). "Nonetheless, it was reported that without the innate proton pump ATP12A activity and airway acidification, CFTR-deficient mice are free from opportunistic Staphylococcus aureus respiratory infection, which makes airway acidification the deciding factor of murine opportunistic lung infections." (PMID 34867864, 2021). "Before the advent of CFTR modulators, CFRD management consisted in the early introduction of insulin in order to reduce the effects of a catabolic state on respiratory infections, lung function and weight loss." (PMID 40688702, 2025). "Almost 40% had a respiratory infection by P. aeruginosa, 45.5% were taking inhaled steroids, 35.7% azithromycin, 27.3% other systemic antibiotics, and 25.2% were being treated with CFTR modulators." (PMID 36009545, 2022). "Factors that contribute to the development of CF-related bone disease include vitamin D and vitamin K deficiency, malnutrition, calcium deficiency, delayed puberty and hypogonadism, reduced physical activity, respiratory infections and systemic inflammation, glucocorticoids, and CFTR dysfunction." (PMID 41300552, 2025). "However, some recent studies suggest that SLC6A14 may play an important role in the response to respiratory infection and fluid secretion related to CFTR." (PMID 32166393, 2020). "Mutations in the CFTR gene encode a nonfunctional chloride channel, causing a broad range of deleterious effects including obstructive lung disease and increased susceptibility to respiratory infections, pancreatic disorders, and reduced fertility in both males and females." (PMID 38952711, 2024). "Because mucociliary clearance is the airway’s most important physical defense and depends on proper fluid volume and mucus rheology, lack of proper CFTR function and failure to properly clear inhaled/inspired bacteria results in increased incidence of both upper and lower respiratory infections." (PMID 36742335, 2023).
Airway obstruction (33 papers, 2006 to 2026). Obstruction of conducting airways of the lung. "Environmental arsenic exposure is associated with impaired CFTR function, as demonstrated by elevated sweat chloride concentrations, and airway obstruction." (PMID 39399016, 2024). "CF-causing mutations in the CF transmembrane conductance regulator (CFTR) lead to impaired chloride and bicarbonate secretion which results in the dehydration of the airway surface liquid layer, mucus plugging, and airway obstruction." (PMID 29216201, 2017). "Additionally, the patient's CFTR gene mutation resulted in impaired ion transport and reduced mucociliary clearance, leading to gradual mucus accumulation, airway obstruction, and subsequent ventilation impairment with hypoxia." (PMID 40933694, 2025). "The increased percentage FEV0.4/FVC in the CFTR-F508del ferrets was unanticipated, since this ratio is most often reduced or normal in CF adolescents and adults, indicating obstructive lung disease (reduced FEV) with a reduction in FVC." (PMID 38646935, 2024). "Single-gene mutations in the Cystic Fibrosis Transmembrane Conductance Regulator (CFTR) gene result in airway obstruction and impaired mucociliary clearance and as such characterize the pulmonary component of the disease." (PMID 37011456, 2023). "In CF, defective function of CFTR in airway epithelial cells and submucosal glands results in chronic involvement of the respiratory tract, manifested by progressive airway obstruction that begins early in life." (PMID 16938132, 2006). "Early assessment of airway obstruction, pulmonary hyperinflation and gas trapping in addition to ventilation inhomogeneities and in conjunction with CFTR genotyping provides a means for monitoring functional progression in CF disease." (PMID 17137500, 2006). "The absence of CFTR causes mucus dehydration, failed MC, airway obstruction, opportunistic infection, and inflammation." (PMID 41237141, 2025). "Thus, our work to elucidate the ASM-specific effects of CFTR dysfunction in an animal model is critical to understand the nature of airway obstruction and improve clinical care for people with CF." (PMID 37568151, 2023). "CF can be caused by mutations in the CF transmembrane conductance regulator (CFTR) gene, affecting mucus production in the lung and digestive organs, which commonly leads to life-threatening airway obstructions." (PMID 33532672, 2021). "Further, asthmatic individuals heterozygous for CFTR had decreased pulmonary function and airway obstruction in comparison to those without mutant CFTR alleles." (PMID 24517344, 2014). "In addition, defective function of CFTR in airway epithelial cells and submucosal glands results in chronic involvement of the respiratory tract, manifested by progressive airway obstruction that begins early in life." (PMID 16938132, 2006). "The β-ENaC mouse has provided a useful alternative to CF mice as it models lower airway obstruction, although it is not suitable for all applications (e.g. trialling CFTR-directed therapies) as CFTR expression and function are unaffected." (PMID 29609604, 2018). "Loss of CFTR function in non-ASM tissue types, such as the pulmonary epithelium, may also drive AHR and airway obstruction; a conditional epithelial CFTR knockout model would allow this to be tested." (PMID 37568151, 2023).
breast carcinoma (33 papers, 2014 to 2025). "Low expression of CFTR is associated with poor prognosis in patients with colon cancer, breast cancer, head and neck cancer, and lung cancer." (PMID 41003841, 2025). "In the issue, 47 out of 1800 patients (2.6%) were carriers of CFTR pathogenic genetic variants: 0.028 (42/1525) (2.8%) among breast cancer patients, 0.017 (3/181) (1.7%) among colorectal cancer patients and 0.021 (2/94) (2.1%) among ovarian cancer patients." (PMID 37175647, 2023). "CFTR modulator therapy improves conception ability, women are pushed to use OCPs more, which is a risk factor for breast cancer." (PMID 36941680, 2023). "The present study additionally evaluated the frequency of pathogenic variants of the CFTR gene in 1525 patients with breast cancer, 181 patients with CRC and 94 patients with OC." (PMID 37175647, 2023). "The mRNA level of CFTR is downregulated and the CFTR protein level is decreased in breast cancer samples that associates with poor prognosis." (PMID 36941680, 2023). "Hypermethylation of CFTR in patients with breast cancer is associated with the development of invasive carcinoma." (PMID 37175647, 2023). "CFTR mutations were also reported to suppress breast cancer growth in mice by elevating extracellular ATP levels." (PMID 32365523, 2020). "CFTR deficiency is associated with reduced disease-free survival in human colorectal cancer, poor prognosis in human breast cancer, and poor survival rates in young patients with NSCLC." (PMID 32182826, 2020). "Meanwhile, mutations and low-penetrance polymorphisms in the CFTR gene have been found in patients with various cancers, including pancreatic cancer, breast cancer, cervical cancer, melanoma, prostate cancer and lung cancer." (PMID 25502083, 2015). "CFTR mutation may be cancer protective as elevated extracellular ATP (adenosine triphosphate) is known to inhibit breast cancer cell line growth in vitro and in vivo." (PMID 36941680, 2023). "However, CFTR is potentially recurrently mutated by chance because of its large size and its involvement in breast carcinogenesis is controversial, thus, it cannot be considered as a potential breast cancer candidate gene." (PMID 29879995, 2018). "The largest proportion of the CFTR genetic alterations were found in women with breast cancer (BC): 41 out of 47 carriers (87%)." (PMID 37175647, 2023). "Hormonal targeted therapies in breast cancer like selective estrogen receptor modulators (i.e. raloxifene, tamoxifen) increases CFTR expression." (PMID 36941680, 2023). "It has previously been shown that the CFTR gene promoter is hypermethylated in tumor tissue in breast cancer, while the level of CFTR messenger RNA decreases." (PMID 37175647, 2023). "Downregulation of CFTR in breast cancer cells enhances malignant phenotypes and is deeply involved in a poor prognosis for breast cancer." (PMID 38203460, 2023). "Is demonstrated, that chemotherapy used for breast cancer affects the CFTR channel and CFTR modulator therapy has frequent side effects on breast tissue." (PMID 36941680, 2023). "Hypermethylation of the CFTR promoter has also been observed in head and neck cancer and non-small cell lung cancer, bladder cancer, liver cancer and breast cancer." (PMID 37644544, 2023). "Treatment of breast cancer cells with decitabine (10 μM), which removes hypermethylation, leads to the restoration of CFTR mRNA expression." (PMID 37175647, 2023). "Since hyaluronan is exported from human breast carcinoma cells by CFTR, citrate and isocitrate were tested for their influence on hyaluronan export in cell culture." (PMID 36296967, 2022). "CFTR also suppresses metastasis in non-small cell lung cancer, nasopharyngeal carcinoma and breast cancer." (PMID 34830864, 2021). "While CFTR has been proposed as a tumor suppressing gene in tumors of the intestine, lung, and breast cancers, its effects in head and neck cancer (HNC) have yet to be investigated." (PMID 32182826, 2020).